NSUN2 (NOP2/Sun RNA methyltransferase 2)
Diseases named in the same sentence as NSUN2 in open-access papers (continued):
Sharing a sentence is not in itself a finding about the gene and the disease.
esophageal squamous cell carcinoma (28 papers, 2020 to 2025). Esophageal squamous cell carcinoma (ESCC) is a type of esophageal carcinoma (EC) that can affect any part of the esophagus, but is usually located in the upper or middle third. "GRB2 is a critical upstream linker that promotes Raf phosphorylation that is regulated by NSUN2 in esophageal squamous cell carcinoma." (PMID 36183976, 2023). "NSUN2 overexpression was linked to poor prognosis of esophageal squamous cell carcinoma (ESCC) patients, whereas its silencing suppressed in vivo tumorigenesis and progression of ESCC in Nsun2-KO mice." (PMID 37612540, 2023). "In esophageal squamous cell carcinoma, NSUN2 and LIN28B enhance the stability of GRB2 mRNA in an m5C-dependent manner, thereby facilitating cancer emergence and progression." (PMID 36532062, 2022). "By stabilizing the mRNA of GRB2, NSUN2 facilitates the development of esophageal squamous cell carcinoma." (PMID 36348434, 2022). "LncRNA NMR is a novel NSUN2 methylated lncRNA, upregulated in esophageal squamous cell carcinoma (ESCC), functioned as a key factor of ESCC progress." (PMID 34888249, 2021). "One study showed that NSUN2 enhances tumor metastasis by m5C methylation of NMR lncRNA in esophageal squamous cell carcinoma (ESCC)." (PMID 34272618, 2021). "Furthermore, NSUN2-mediated lncRNA NMR promotes tumor progression by controlling the expression of important oncogenic drivers in esophageal squamous cell carcinoma, such as matrix metalloproteinase 10 (MMP10) and MMP3." (PMID 38351139, 2024). "LIN28B also has a similar structure and stabilizes growth factor receptor-bound protein 2 (GRB2) mRNA in an NSUN2-dependent manner in esophageal squamous cell carcinoma (ESCC), thus indicating that it is a potential m5C reader." (PMID 35562754, 2022). "A recent study on esophageal squamous cell carcinoma (ESCC) identified lncRNA NMR (NSun2 methylated lncRNA), which is highly expressed in ESCC and plays a key regulatory role in the tumorigenesis and drug resistance of ESCC." (PMID 32978516, 2020). "Similarly, NSUN2 overexpression promotes the development of esophageal squamous cell carcinoma (ESCC) by stabilizing mRNAs involved in the PI3K/Akt and MAPK signaling pathways." (PMID 41446042, 2025). "Here, by detecting the transcriptome-wide m5C profiling in esophageal squamous cell carcinoma (ESCC), we showed increased m5C methylation in ESCC tumors due to the overexpressed m5C methyltransferase NSUN2." (PMID 34345012, 2021). "In esophageal squamous cell carcinoma (ESCC), NSUN2 is overexpressed and plays an oncogenic role." (PMID 35562754, 2022). "For example, NSUN2 promotes tumor metastasis and cisplatin resistance by methylating NMR (also known as LINC01672) ncRNA, which in turn recruits BPTF and promotes the expression of matrix metalloproteinase 3 (MMP3) and MMP10 in esophageal squamous cell carcinoma." (PMID 37612540, 2023). "In esophageal squamous cell carcinoma (ESCC), lncRNA NMR methylated by NSUN2 combines with the chromatin regulator BPTF to promote the expression of MMP3 and MMP10 via the ERK1/2 pathway; thus, promoting the progression of ESCC." (PMID 34777473, 2021).
bladder cancer (18 papers, 2020 to 2025). "For instance, NSUN2 promotes gastric and bladder cancer progression, and its polymorphism rs13181449 C>T is associated with reduced neuroblastoma susceptibility through diminished NSUN2 expression and lower m5C levels." (PMID 40984038, 2025). "We explored the role of NSUN2 in the clinical outcome of bladder cancer by analyzing relevant data from public databases." (PMID 41354740, 2025). "NSUN2, the main enzyme catalyzing m5C formation, has been demonstrated to promote tumorigenesis in bladder cancer, hepatocellular carcinoma, breast cancer, and gastric cancer by regulating m5C modification at the transcriptome level." (PMID 36792587, 2023). "For example, NSUN2‐mediated m5C modification promotes the pathogenesis of bladder cancer by enhancing the binding of YBX1 to HDGF and thereby promotes its expression." (PMID 37228185, 2023). "For example, YBX1 has been found to be able to work with NSUN2 to stabilize HDGF mRNA to promote the progression of bladder cancer." (PMID 36792587, 2023). "In human bladder cancer cells, it was reported that many oncogenic mRNAs were hypermethylated by NSUN2." (PMID 32101138, 2020). "NSUN2 can stabilize the mitotic spindle to promote tumor cell proliferation and was used to identify several targets reported in gallbladder carcinoma, bladder cancer and several tumors." (PMID 32974125, 2020). "In bladder cancer, many oncogenic RNAs harbor hyper-methylated m5C sites, which are catalyzed by NSUN2." (PMID 32101138, 2020). "Previous studies have demonstrated that overexpression of YBX1 could accelerate PC growth and recognize m5C modification catalyzed by NSUN2, thereby promoting pathogenesis of bladder cancer." (PMID 37393317, 2023). "NSUN2, for example, may stabilize the mitotic spindle, promoting tumor cell proliferation, and has been utilized to discover many targets in gallbladder carcinoma, bladder cancer, and a variety of malignancies." (PMID 35211172, 2022). "In addition, NSUN2 has been found to promote the development and progression of bladder cancer." (PMID 35978830, 2022). "Bladder cancer research has shown that NSUN2 co-exists with Aly/REF export factor (ALYREF), contributing to bladder cancer proliferation, invasion, and poor prognosis." (PMID 40809690, 2025). "NSUN2 has also been reported to stabilize HDGF mRNA via m5C and to promote the progression of bladder cancer." (PMID 36792587, 2023). "As the key m5C methyltransferase, NSUN2 (NOP2/Sun domain family, member 2) has been demonstrated to be overexpressed in a wide range of malignancies, including cancers of bladder, prostate, kidney, cervix, esophagus, stomach, liver, thyroid and breast." (PMID 37393317, 2023). "In bladder cancer (BLCA), NSUN2, IGF2BP2, YTHDC1, ALKBH5, TRDMT1, and ZC3H13 were identified, with NSUN2—a 5-methylcytosine (m5C) writer—previously shown to promote tumorigenesis and cancer stemness by stabilizing CCND1 mRNA and driving epithelial–mesenchymal transition." (PMID 40565233, 2025). "To validate whether NSUN2 and SOCS3 still plays a similar role in BC patients, we isolated TAMs from human bladder cancer specimens with FACS described as above." (PMID 41354740, 2025). "In bladder cancer, m5C reader YBX1 recognized NSUN2‐induced m5C modification in 3′ UTR of hepatoma‐derived growth factor (HDGF) mRNA and further maintained its stability, therefore driving the oncogenic molecular mechanism of HDGF in bladder cancer." (PMID 38721006, 2024). "In addition, NSUN2 promotes the expression of heparin‐binding growth factor (HDGF) and promotes pathogenesis of the bladder cancer." (PMID 37228185, 2023). "Additionally, NSUN2 collaborates with YBX1 to stabilize HDGF3 mRNA by recruiting ELAVL1 and targeting the m5C modification site in the HDGF 3′untranslated region, ultimately promoting bladder cancer progression." (PMID 40809690, 2025).
glioma (18 papers, 2020 to 2025). A benign or malignant brain and spinal cord tumor that arises from glial cells (astrocytes, oligodendrocytes, ependymal cells). "The oncogenic function of NSUN2 is underscored by studies showing that NSUN2 knockout or knockdown impairs migration and metastasis in models of esophageal squamous carcinoma, glioma, and others." (PMID 41301491, 2025). "Taken together, our study provided an explainable theory that ANXA2/NSUN2/YBX1 axis modulated the generation of B7‐H3 isoform in glioma cells." (PMID 39048916, 2024). "Our findings have uncovered a series of factors (ANXA2/NSUN2/YBX1) that can determine the alternative generation of different isoforms of B7‐H3 in glioma." (PMID 39048916, 2024). "NSUN2 appeared in the glioma cells expressing 2Ig, but disappeared in cells expressing 4Ig, which aroused our concern." (PMID 39048916, 2024). "In the human glioma cell line U87, NSUN2 mediates tumor cell migration by regulating the autotaxin (ATX)- lysophosphatidic acid (LPA) axis." (PMID 35562754, 2022). "For example, NSUN2 methylation can promote ATX exudation, enhance mRNA transcription, and influence the migration of glioma cells U87 through the NSUN2–ATX–LPA axis." (PMID 35574373, 2022). "In the human glioma cell line U87, knockdown of NSun2 decreased ATX protein levels, whereas overexpression of NSun2 elevated ATX protein levels." (PMID 33093178, 2020). "We obtained six genes associated with prognosis (P < 0.01), among which NOP2, NSUN2, NSUN4, NSUN5, and NSUN7 acted as risk factors (HR > 1), and NSUN6 played a protective role (HR < 1) in gliomas." (PMID 32974125, 2020). "In gliomas, NSUN2 could methylate autotaxin mRNA, thus increasing autotaxin protein expression and promoting tumor cell migration." (PMID 41463199, 2025). "NSUN2 methylates the 3′-UTR of ATX mRNA at the C2756 site in the human glioma cell line U87." (PMID 40860147, 2025). "Because NSUN2 primarily acts as a 5‐methyltransferase for RNA, whether NSUN2‐mediated 2Ig of B7‐H3 selection in glioma was modulated via RNA methylation needs to be addressed." (PMID 39048916, 2024). "Coincidentally, the presence of the weakened expression of NSUN2 in glioma cells and tissues with robust abundance of 2Ig, suggesting that the abundance of NSUN2 might be related to the production of 2Ig." (PMID 39048916, 2024). "While NSUN2 and NSUN4 are highly expressed in glioma, single-cell bioinformatic analysis has revealed that malignant cells present the lowest NSUN5 expression levels among the different cell types that make up the tumour mass." (PMID 40860147, 2025). "By comparing among five glioma cells, we have finally found three proteins ANXA2/NSUN2/YBX1 that can explain the phenotypes in different cells." (PMID 39048916, 2024). "The axis of NSUN2/YBX1 can promote the generation of 2Ig of B7‐H3 in glioma, and we speculate that the abundant 2Ig takes up too much of the cell surface, causing the T cells to fail to recognize enough 4Ig, allowing the glioma to become immune escape capability." (PMID 39048916, 2024). "In low-grade gliomas, several m5C regulators of DNA and RNA are upregulated, including NSUN3, TET2, DNMT2, ALYREF, DNMT3b, DNMT1, NOP2, and NSUN2." (PMID 35562754, 2022). "Similarly, NSUN2 methylates LINC00324 via m5C modifications, increasing its stability and expression, which promotes glioma angiogenesis." (PMID 41463199, 2025). "In glioma, NSUN2-mediated m5C modification in the 3’-UTR of ATX mRNA strengthens its interaction with the reader protein ALYREF, facilitating nuclear export of the transcript and promoting glioma cell migration." (PMID 41446042, 2025). "In glioma, methylation of ATX mRNA at the 3′-UTR by NOP2/Sun RNA methyltransferase 2 (NSun2) enhances ATX mRNA nuclear-to-cytoplasm transportation and upregulates its expression, a sequence of events that leads to enhanced migratory capacity in glioma cells." (PMID 38607068, 2024).
glioma (continued). "Studies have shown that NSUN2 can increase the stability of LINC00324 by regulating m5C modification, thereby regulating glioma angiogenesis, and can also enhance the translation of intercellular adhesion molecule 1 (ICAM-1) to reduce inflammatory responses in the vascular endothelium." (PMID 38764010, 2024). "We believe that the illustration of ANXA2/NSUN2/YBX1 regulatory axis is a prerequisite to address the complicated pattern of B7‐H3 in glioma, which again highlights the problem of immunotherapy not being universally effective in the cancer population." (PMID 39048916, 2024). "The expression of NOP2, NSUN2, NSUN4, NSUN5, and NSUN7 were positively correlated in gliomas." (PMID 32974125, 2020).
Intellectual disability (18 papers, 2015 to 2025). "Several mutations in the NSUN2 gene are identified as the primary cause of autosomal-recessive forms of intellectual disability." (PMID 39673800, 2025). "In this study, we demonstrate that a nucleoplasm-localized G679R NSUN2 mutant, linked to intellectual disability, diminishes NSUN2-mediated tRNA m5C in human cell lines and Drosophila." (PMID 39673800, 2025). "While most identified NSUN2 mutations causing intellectual disability are nonsense mutations, G679R remains the only reported missense mutation of NSUN2." (PMID 39673800, 2025). "The G679R NSUN2 mutant located in the nuclear cytoplasm is associated with intellectual disability and reduces NSUN2-mediated tRNA m5C in human cell lines and fruit flies." (PMID 41462962, 2025). "The m5C RNA modifications or NSUN2 deletions are associated with intellectual disability and cancer." (PMID 40870000, 2025). "Recently, 16 loss-of-function (LoF) NSUN2 mutations were identified in 30 patients with intellectual disability/developmental delay (ID/DD) and growth retardation." (PMID 38643142, 2024). "Pathogenic mutations in FTSJ1 and TRM4/NSUN2, involving in the process, are associated with intellectual disabilities." (PMID 39296543, 2024). "Similar phenotypes (intellectual disability and facial dysmorphism) were observed in humans with homozygous NSUN2 mutation, suggesting that NSUN2 plays a crucial role in intellectual disability prevention." (PMID 37612540, 2023). "Missense mutation c.2035G > A (p.Gly679Arg) in NSUN2, a m5C methyltransferase that functions in spindle assembly during mitosis as well as chromosome segregation, caused autosomal-recessive intellectual disability." (PMID 37612540, 2023). "Evidence for the importance of solely NSUN2-mediated m5C in human health and disease was first provided by individuals with a loss-of-function mutation in NSUN2, displaying intellectual disability (ID), facial dysmorphism, and distal myopathy." (PMID 34389722, 2021). "For instance, knockout of NSUN2 in mice causes male infertility and reduced growth, while mutations in human NSUN2 are involved in intellectual disability." (PMID 33199375, 2021). "Mutations in NSUN2 are associated with microcephaly and intellectual disabilities in mice and humans, and the accumulation of abnormal 5′ tRNA fragments in NSun2 knockout mice causes cellular stress responses and neuronal apoptosis." (PMID 29880782, 2018). "While absence of Ncl1 is tolerated without severe phenotypes in yeast, mutation of the human NCL1 orthologue NSUN2 is linked to intellectual disability, like several other mutations affecting tRNA modifiers." (PMID 30143741, 2018). "Dubowitz-like syndrome associated with intellectual disability is also linked to mutations in Nsun2." (PMID 28536502, 2017). "Mutations in FTSJ1 are associated with mental retardation and mutations in NSUN2 with intellectual disability as well as cardiac diseases, indicating their importance in human development and health." (PMID 28282871, 2017). "Whole-exome sequencing has demonstrated a homologous mutation (c.1020delA) in the NSUN2 gene, which is caused by a frameshift and premature stop codon and leads to decreased NSUN2 mRNA levels in children and may also cause intellectual disability." (PMID 41462962, 2025). "Besides several nonsense mutations, one G679R missense mutation of NSUN2 causes intellectual disabilities in humans." (PMID 39673800, 2025). "NSun2 is one of the methyltransferases known to facilitate methylation of non-coding RNAs, whose loss of function due to autosomal-recessive mutations can cause disorders that are associated with intellectual disability in humans." (PMID 36357715, 2023).
Intellectual disability (continued). "METTL16 had the highest overall number of intellectual disability co-regulated proteins with 55 and was the only effector protein which had NSUN2 listed as an ID co-regulated protein." (PMID 39499421, 2025). "Several RNA methyltransferases have been linked to intellectual disability, such as the FtsJ RNA 2’-O-Methyltransferase 1 (FTSJ1), the TRNA Methyltransferase 1 (TRMT1) and NSUN2." (PMID 37612540, 2023). "NSun2 deficiency has a negative impact on learning and memory in fruit flies, mice and causes intellectual disability and neurological abnormalities in human." (PMID 36357715, 2023). "Moreover, inhibition of angiogenin-mediated tRNA cleavage rescues the elevated stress levels of NSUN2(−/−) cells during neurodevelopment in vivo, suggesting the protective role of NSUN2 modification in human neurocognitive and intellectual disabilities." (PMID 30477220, 2018). "Similarly, NSUN2 function is connected to intellectual disability in humans." (PMID 39673800, 2025). "Indeed, human patients lacking NSun2 are characterized by intellectual disability as well as other neurodevelopmental deficits." (PMID 26582006, 2015).